SRRM4 (serine/arginine repetitive matrix 4)
Diseases named in the same sentence as SRRM4 in open-access papers (continued):
Sharing a sentence is not in itself a finding about the gene and the disease.
tumor (continued). "Gene expression analysis of 81 human SCLC primary tumours with RNA-seq data showed that abnormal high expression of SRRM4 corresponds to lower REST expression." (PMID 31110284, 2019). "GASO against SRRM4 successfully reduced the tumor formation in vivo by suppressing specifically SRRM4 expression." (PMID 31110284, 2019). "In our previous study, SCLC cells expressing high levels of SRRM4 were implanted subcutaneously and were found to induce tumor formation." (PMID 31110284, 2019). "Furthermore, altered REST splicing was also found to mediate the anti-tumor effects of SRRM4 targeting in prostate cancer cells." (PMID 37892159, 2023). "The altered REST splicing was found to mediate the anti-tumor effects of SRRM4 targeting in SCLC." (PMID 37892159, 2023). "We further tested whether SRRM4 expression correlates with other tumor features apart from proliferation." (PMID 33621242, 2021). "Overall, these results validate the hypothesis that SRRM4 splicing activity can influence tumor growth in vitro and in vivo." (PMID 33621242, 2021). "In support of our hypothesis, we observed a negative correlation (RSpearman = −0.36, p < 2.2e-16) between the MI and SRRM4 expression in tumor samples, while a positive correlation was observed at the promoter methylation level (RSpearman = 0.45, p < 2.2e-16)." (PMID 33621242, 2021). "We show that this silencing is favorable for tumor growth, as decreased SRRM4 expression in tumors is correlated with an increase in mitotic gene expression, and up-regulation of SRRM4 in cancer cell lines dose-dependently inhibits proliferation in vitro and in a mouse xenograft model." (PMID 33621242, 2021). "While SRRM4 is the only one of these factors that changes significantly and in the same direction across all tumor types included in our study, others also display significant expression changes in specific tumor types." (PMID 33621242, 2021). "Interestingly, our results suggest that SRRM3 is not involved, despite being thought to regulate similar targets as SRRM4, as its expression is increased in a majority of tumor types." (PMID 33621242, 2021). "We also found that each exon had significant negative correlations with MI gene signature in a majority of tumor types, suggesting that down-regulation of these exons might contribute to the growth advantage obtained by tumors with decreased SRRM4." (PMID 33621242, 2021). "We hypothesized that small changes in SRRM4 expression would have measurable effects on proliferation over a longer period of time, such as during tumor evolution, which occurs on a timescale of years instead of days." (PMID 33621242, 2021). "As expected, both induced tumors had significantly increased inclusion of all microexons, and SRRM4 target exons specifically, compared to the uninduced tumor, as well as up-regulated expression of neural genes similar to that observed in the cell lines in vitro." (PMID 33621242, 2021). "Within SCLC cells the degree of SRRM4 expression varied suggesting that it may contribute to the heterogeneity of tumor progression and toxicity in patients." (PMID 31110284, 2019). "In agreement with the known role of SRRM4 as a key regulator of microexon splicing, we found that a majority of the differentially included SRRM4 targets were ≤27 nucleotides in length, and the proportion significantly decreasing in tumors was larger than those increasing for every tumor type." (PMID 33621242, 2021).
tumor (continued). "Surprisingly, we find that not only are SRRM4 and its microexon program globally down-regulated in cancer despite having low basal inclusion in normal nonneural tissues, but also in fact SRRM4 is the most consistently down-regulated across tumor types out of all SFs analyzed." (PMID 33621242, 2021). "Consequently, it is possible that SRRM4 may act in conjunction or synergy with tumor microenvironment factors or regulators to further drive the development and progression of CRPC-NE." (PMID 29666783, 2018). "In searching for other SRRM4-targeted RNA splicing that may contribute to NEPC progression, we have found a highly expressed splice variant of the MYST/Esa1-associated factor 6 (MEAF6) gene, MEAF6-1, in NEPC tumor samples." (PMID 28427194, 2017). "SRRM4 ASO successfully repressed SRRM4 mRNA in SCLC cell culture and suppressed tumor formation in vivo." (PMID 36650528, 2023). "Repression of SRRM4 mRNA induced modified alternative splicing producing REST, followed by anti-tumor effects." (PMID 36650528, 2023). "To further demonstrate the regulatory impact of SRRM4 activity on SRRM4 target inclusion levels, we correlated the expression levels of SRRM4 with the PSI of its target exons across TCGA tumor samples." (PMID 33621242, 2021). "To experimentally mimic the competition between cells with high and low SRRM4 expression during tumor evolution, we performed a coculture experiment where MDA-MB-231 cells with inducible expression of either WT or DM SRRM4 were mixed at a 1:1 ratio." (PMID 33621242, 2021). "Through RNA splicing, SRRM4 simultaneously reprograms REST functions to confer a neuroendocrine phenotype in AdPC cells and re-directs MEAF6 functions to stimulate tumor cell proliferation and invasion." (PMID 28427194, 2017). "Although L687-induced knockdown needs to be considered, the in vitro results showed that L687 did not alter SRRM4 expression in N417 cells, suggesting L687 itself is not responsible for SRRM4 knockdown in tumours." (PMID 38621757, 2024). "We did not observe any clear trend of SRRM4 expression changes across different tumor/node/metastasis (TNM) stages nor was there a significant correspondence of SRRM4 expression levels with patient survival in any tissue type (Kaplan–Meier method, q < 0.05, false discovery rate [FDR] corrected)." (PMID 33621242, 2021). "In the tumor part, SRRM4 mRNA was decreased or not detected after gASO administration." (PMID 31110284, 2019). "However, REST knockdown in LNCaP cells does not allow a t-NEPC xenograft to develop, supporting the notion that SRRM4-mediated REST gene splicing leads to neuroendocrine differentiation but does not induce proliferation sufficient for clonal expansion and t-NEPC tumor establishment." (PMID 28427194, 2017). "Furthermore, for each individual SRRM4 exon, we calculated a Spearman correlation coefficient between the PSI of the exon and MI across tumor samples and found a strong negative association between the direction of this correlation for each exon and its ΔPSI in tumors (p = 3.68e-16, binomial test)." (PMID 33621242, 2021). "Of the remaining one-third of SRRM4 target exons with an average PSI > 5 in normal nonneural tissues, a majority (64%) were found to significantly decrease in at least 1 tumor type (red points)." (PMID 33621242, 2021). "Interestingly, when a proved NEPC driver gene SRRM412 was exogenously introduced into PCa cells, tumor cells almost without EHF expression, just like DU145 cells, could acquire a pluripotency gene network that could not be induced by SRRM4 in cells with EHF endogenous expression." (PMID 33414441, 2021).
cancer (11 papers, 2017 to 2024). A tumor composed of atypical neoplastic, often pleomorphic cells that invade other tissues. "In particular, out of 15 cancer genes tested, 10 of them raised significant associations (p < 0.05), with the presence of 8 of them being associated with a lower SRRM4 expression." (PMID 33621242, 2021). "We did detect significant associations between SRRM4 expression and mutations in certain cancer genes, where the presence of mutations in those genes are generally associated with a lower expression of SRRM4." (PMID 33621242, 2021). "Intracellular miR-4516 in 22Rv1 cells increased after REST_SSO treatment, possibly because the number of cells expressing SRRM4 was reduced or cells, such as cancer stem cells, expressed miR-4516." (PMID 39377066, 2024). "Abnormal expression of SRRM4, which causes the loss of REST activity through alternative splicing to sREST, promotes the emergence of neuroendocrine phenotypes of cancers." (PMID 36650528, 2023). "Most recently, the splicing program controlled by SRRM4 was shown to play a role in cancer proliferation and differentiation." (PMID 36650528, 2023). "Further, this proliferation inhibition is accompanied by induction of neural-like expression and splicing patterns in cancer cells, suggesting that SRRM4 expression shifts the cell state away from proliferation and toward differentiation." (PMID 33621242, 2021). "Correspondingly, we observe marked inhibition of cancer cell proliferation with SRRM4 overexpression both in vitro and in a mouse xenograft model, accompanied by induction of neuron-like splicing and expression patterns." (PMID 33621242, 2021). "These differentially spliced exons were significantly enriched for experimentally determined SRRM4 targets in every cancer type tested (p < 10−6; Fisher test)." (PMID 33621242, 2021). "We map this decreased expression to a strong increase in methylation of SRRM4 promoters, indicative of epigenetic silencing of SRRM4 expression in cancer." (PMID 33621242, 2021). "NE tumors with SOX2 expression are therefore likely the exception to the here-described selection for silencing of SRRM4 in cancer." (PMID 33621242, 2021). "Taken together, these findings demonstrate a global and significant pattern of silencing of SRRM4 in cancer." (PMID 33621242, 2021). "As such, the finding that SRRM4 and its microexon splicing program are silenced in tumors contributes an important new element to the overall picture of splicing dysregulation in cancer." (PMID 33621242, 2021). "We therefore surmise that silencing of SRRM4 provides a selective advantage to cancer cells by shifting the cell state away from differentiation and toward proliferation." (PMID 33621242, 2021). "We show that SRRM4 expression and exon inclusion changes anticorrelate with mitotic gene expression in tumors, signifying an inverse relationship with cancer cell proliferation." (PMID 33621242, 2021). "Taken together, these findings provide a mechanistic explanation for the observed decrease of SRRM4 expression and microexon inclusion in cancer." (PMID 33621242, 2021). "Prior studies of SRRM4 in cancer to date have focused exclusively on a rare class of tumors known as neuroendocrine (NE) tumors (0.5% to 2% of malignancies in adults), due to their shared properties with neural or NE tissues." (PMID 33621242, 2021). "Despite the high frequency of AS alterations in cancer, the degree of consistency of SRRM4 silencing across tissues was particularly striking." (PMID 33621242, 2021). "This multi-functional property of SRRM4 ultimately provides cancer cells the ability to develop therapy resistance and develop into CRPC-NE." (PMID 29666783, 2018). "Additional correlation analysis between SMARCA4 and SRRM4 across the pan-cancer CCLE dataset revealed two well-defined groups: one including cell lines expressing SMARCA4 and lacking SRRM4, and another group with a strong positive correlation between these genes." (PMID 39080761, 2024).
cancer (continued). "Our results suggest that this down-regulation provides tumors with a growth advantage, as decreased SRRM4 expression in tumors is correlated with an increase in mitotic gene expression, and up-regulation of SRRM4 in cancer cell lines dose-dependently decreases proliferation." (PMID 33621242, 2021). "The inclusion of a 12-nucleotide exon in TEAD2 (event ID: HsaEX0064372) is one of the most consistently decreased microexons in tumors (6/9 tissue types in our dataset) and is SRRM4 regulated, as evidenced by its up-regulation in all 6 cancer cell lines after SRRM4 overexpression." (PMID 33621242, 2021). "Thus, microexon splicing changes affecting the activity of multiple genes with known roles in cancer likely contribute to the antiproliferative phenotype of SRRM4." (PMID 33621242, 2021). "The similarity between changes observed in the neuronal differentiation dataset and the cell lines with SRRM4 overexpression further supports the hypothesis that SRRM4 promotes differentiated neuron-like expression and splicing patterns in cancer cells." (PMID 33621242, 2021). "In addition, we also identified two well-known neuroendocrine genes, ONECUT2 and SRRM4, that demonstrated cancer-specific gene body DNA methylation alterations, and which also positively correlated with gene expression in MCC." (PMID 34399838, 2021). "To test the hypothesis that SRRM4 expression affects cancer cell proliferation, we generated several stable cell lines with tetracycline-inducible expression of SRRM4." (PMID 33621242, 2021). "In this review, a number of cancer-specific spliceosomal factors have been discussed, including PSF and SRRM4." (PMID 30939845, 2019). "Taken together, these results suggest a global silencing of SRRM4 in cancers, beyond their normally low inclusion levels in nonneural tissues." (PMID 33621242, 2021). "Other SRRM4 target genes such as PTPRF and PTK2, have known functions in regulating cell proliferation or apoptosis, suggesting that these genes may enable cancer cell to gain growth and survival advantages under chemo- or hormonal therapies." (PMID 28978002, 2017). "Therefore, our finding that SRRM4 is further silenced in cancers of nonneural origin suggests that low levels of SRRM4 outside of the brain do have a physiologic role as proliferation brakes." (PMID 33621242, 2021).
adenocarcinoma (7 papers, 2017 to 2024). A common cancer characterized by the presence of malignant glandular cells. "We report that through generating neuronal-specific splice variants of target genes, SRRM4 can induce neuroendocrine phenotypes and neuronal-like cellular morphology in adenocarcinoma (AdPC) cells and transform AdPC cells into NEPC xenografts." (PMID 28978002, 2017). "The RNA splicing factor SRRM4 is capable of driving adenocarcinoma cell progression toward NEPC with concurrent upregulation of NEPC‐specific biomarkers." (PMID 33009820, 2021). "The LnNE model is generated by introducing exogenous SRRM4 in adenocarcinoma cells." (PMID 28978002, 2017). "This was further evidenced by the ability of SRRM4 to alter cellular morphology and induce the expression of NEPC markers in adenocarcinoma cells." (PMID 39682746, 2024). "One of the RNA splicing factor, RNA splicing factor serine/arginine repetitive matrix 4, SRRM4, was recently identified as a strong stimulator of adenocarcinoma cells to express NEPC biomarkers under androgen receptor pathway inhibition." (PMID 33572108, 2021).
neurological disorders (1 paper, 2021). "Moreover, a recent genome-wide CRISPR-Cas9 screen has identified two additional factors, SRSF11 and RNPS1, that contribute to SRRM4-dependent microexon regulation, and these genes have also been implicated in ASD and other neurological disorders." (PMID 33482885, 2021).
SRRM4 also shares sentences with these, for which no sentence is quoted: Ad (2 papers); Alzheimer’s disease (1); anxiety disorder (1); brain disorder (1); brain tumours (1); breast carcinoma (1); centronuclear myopathy (1); colorectal cancer (1); Dystonia (1); glioblastoma (1); hearing loss (1); hematological diseases (1); infection (1); infectious disease (1); movement disorder (1); myotonic dystrophy (1); neurodevelopmental disorder (1); PRLomas (1); psoriasis (1).